SIRT3 (sirtuin 3)
Diseases named in the same sentence as SIRT3 in open-access papers (continued):
Sharing a sentence is not in itself a finding about the gene and the disease.
tumor (continued). "The exact role of sirtuins in cancer remains controversial with dichotomous functions being reported, for example multiple studies have shown that SIRT1, SIRT3 and SIRT5 can act as tumor promoters or tumor suppressors under different cellular conditions, tumor stage and tissue of origin." (PMID 27465020, 2016). "In conclusion, our study demonstrated that down-regulation of selected mitochondrial TS genes such as SIRT3, SIRT4 and MTUS1 in HNSCC indicate aggressive tumor behaviors and may predict an unfavorable clinical outcome." (PMID 26785117, 2016). "Furthermore, a recent study revealed that SIRT3 negatively regulates pancreatic tumor growth by restraining malate-aspartate NADH shuttle, which is critical to sustain glycolysis in tumor cells, via deacetylating glutamate oxaloacetate transaminase (GOT2)." (PMID 27916001, 2016). "In keeping with this, our data indicates that patients whose tumour expresses low levels of SIRT3 were more likely to relapse and die earlier if they did not receive chemotherapy." (PMID 26121130, 2015). "Lack of SIRT3 in MEFs leads to genomic instability and a high frequency of cell transformation mediated by Ras with an increased rate of tumor formation and aging, suggesting that SIRT3 is necessary in prevention of cellular aging and carcinogenesis." (PMID 26121691, 2015). "Multivariate analysis revealed that cytoplasmic SIRT3 (p = 0.062), lymph node status (p = 0.008) and tumour differentiation (p = 0.041) were independent of tumour stage and grade, in influencing disease-free survival." (PMID 26121130, 2015). "Multivariate cox-regression analysis revealed that cytoplasmic SIRT3 (p = 0.02), lymph node status (p = 0.006) and tumour differentiation (p = 0.006) were independent of tumour grade and size, in influencing disease-specific survival." (PMID 26121130, 2015). "This may be part of the mechanism behind SIRT3, SIRT4, and SIRT5 appearing to have tumor-suppressive effects." (PMID 25165814, 2014). "These experiments strongly suggest that aberrant mitochondrial superoxide metabolism plays a significant role in the tumor-permissive phenotype observed in cells lacking Sirt3." (PMID 25332769, 2014). "Both tumoral and peritumoral Sirt3 expression level were not correlated with tumor size, tumor numbers, differentiation, encapsulation or vascular invasion." (PMID 24774224, 2014). "Whereas the preponderance of the evidence suggests that SIRT1 in many contexts promotes cancer metabolism by working in conjunction with HIF and MYC family proteins, SIRT3, SIRT4 and SIRT6 all inhibit distinct aspects of the metabolic alterations observed in tumor cells." (PMID 25085992, 2014). "Furthermore, low expression of SIRT3 was significantly correlated to differentiation (P = 0.013), clinical stage (P = 0.005), serum AFP level (P<0.01), tumor multiplicity (P = 0.026) and relapse (P = 0.028)." (PMID 23272146, 2012). "Results showed that SIRT3 expression in noncancerous tissue was not significantly changed in cases with different tumor differentiation." (PMID 23272146, 2012). "Moreover, a crucial role in the regulation of Warburg effect in cancer cells has been proposed for mitochondrial SIRT3, which belongs to NAD-dependent deacetylase family, already involved in tumour metabolism." (PMID 22666258, 2012). "The differential expression of SIRT3 in tumor and adjacent nontumor tissues appeared statistically significant." (PMID 23272146, 2012). "All these experiments strongly suggest that aberrant mitochondrial superoxide metabolism, at least in part, plays a significant role in the tumor permissive phenotype observed in cells lacking Sirt3." (PMID 22016654, 2011). "Specifically, molecular changes in SIRT3 and SIRT7 expression may contribute to tumour development and disease progression." (PMID 17003781, 2006).
tumor (continued). "For instance, SIRT1 and SIRT3 may preserve redox homeostasis and protect non-malignant cells from oxidative damage, yet the same antioxidant function may also sustain tumor survival under metabolic or chemotherapeutic stress." (PMID 41425553, 2025). "It is to mention that Arg-II-induced suppression of Sirt3 is independent of mtROS in the tumor cells, since inhibiting mtROS with TEMPO does not affect Sirt3 levels, demonstrating that there is no mutual regulation between Sirt3 and mtROS and the enhanced mtROS is due to suppression and Sirt3." (PMID 40177131, 2025). "SIRT3 is downregulated in HCC tumour tissue compared to adjacent non-cancerous tissues." (PMID 40136715, 2025). "Moreover, SIRT3 and SIRT4 have been shown to inhibit tumor cell proliferation." (PMID 41011152, 2025). "Mitochondrial SIRTs (SIRT3, SIRT4 and SIRT5) have been widely reported to regulate a variety of key biological processes, including gene expression, DNA damage repair, metabolism and survival, and have the Janus role in tumorigenesis, either tumor suppressive or oncogenic functions 122-124." (PMID 38773972, 2024). "The observation of decreased acetylation in key glycolytic enzymes following SIRT3 inhibition, notably PGK1 and PGAM, highlights the critical role of acetylation in metabolic enzyme activity regulation, pointing to intricate regulatory networks modulating tumor cell metabolism." (PMID 38542426, 2024). "Because SIRT3 was more highly expressed in GBM samples than in normal brain tissue, we hypothesize that targeting SIRT3 to destroy mitochondrial integrity and homeostasis can damage tumor cells while leaving normal cells healthy." (PMID 38395990, 2024). "Therefore, SIRT4 and SIRT5 potentially inhibit the occurrence and development of ccRCC, whereas high expression of SIRT3, SIRT6, and SIRT7 might have an important tumor-promoting role." (PMID 37096064, 2023). "According to this paper, Sirt3 depletion was followed by the acetylation of glutamine dehydrogenase (GDH) and ensuing suppression of its activity as well as a significant reduction in acetyl-CoA pools with simultaneous induction of autophagic death of tumor cells." (PMID 35938164, 2022). "As a tumor suppressor, acetylation of aconitase (ACO2) could be reversibly regulated by SIRT3." (PMID 35832551, 2022). "Overexpression of SIRT3 has been reported in several OSCC cell lines, while the administration of SIRT3 inhibitors such as sirtinol and nicotinamide enhanced the sensitivity of OSCC cells to radiation and cisplatin treatment via the accumulation of ROS to induce tumor cell apoptosis." (PMID 36060706, 2022). "HDCA leads to oxidative stress and apoptosis in vivo tumor models and displays an action that is functionally opposed to that of TRAP1, as it induces both succinate dehydrogenase and the mitochondrial deacetylase sirtuin-3 (SIRT3), which further enhances succinate dehydrogenase activity." (PMID 34829705, 2021). "SIRT3 and SIRT5 also mediate desuccinylation and deacetylation of SHMT2, respectively, suggesting that suppression of serine catabolism might represent a novel strategy to restrain tumor growth." (PMID 33117804, 2020). "SIRT3 can deacetylate and activate various mitochondrial metabolic enzymes involved in TCA and FAO enzymes, including LCAD, 3-hydroxy-3-methylglutaryl CoA synthase 2 (HMGCS2), isocitrate dehydrogenase 2 (IDH2) and glutamate dehydrogenase (GDH) to block the supply of glycolysis to the tumor cells." (PMID 33109235, 2020). "It is unknown, whether the tumor phenotypes of mice lacking SIRT3 or SIRT4 are primarily based on mitochondria-dependent and/or -independent (i.e., mitotic/microtubule-associated) mechanisms." (PMID 32846968, 2020). "Not surprisingly, SIRT3 has also been found to promote tumor progression in some other cancers." (PMID 32724473, 2020).
tumor (continued). "SIRT3 down-regulates HIF1α and pyruvate dehydrogenase kinase 1 (PDK1) in cholangiocarcinoma, and suppresses the Warburg effect also by the activation of pyruvate dehydrogenase complex (PDC) and the indirect inhibition of the tumor specific isoenzyme hexokinase II (HK II)." (PMID 32117717, 2020). "It is also not clear whether mitochondrial sirtuin deacetylase Sirt3 is a tumor suppressor or a tumor promoter or is it dependent on cell or tumor type." (PMID 32698385, 2020). "Therefore, it can be proposed that SIRT3 exhibits oncogenic properties in the context of HFD-induced tumorigenesis and SIRT3 inhibition might be suggested as a strategy to mitigate the tumor promoting effects of HFD." (PMID 31970087, 2019). "Therefore, SIRT2 activation upon CR and SIRT3 inhibition upon HFD could be explored as new strategies to enhance CR-induced cancer prevention and decrease HFD-induced tumor development, respectively." (PMID 31970087, 2019). "The results showed that 55.1% of tumor tissues (7% of normal tissues) exhibited high level (strong positive), 41.4% of tumor tissues (28% of normal tissues) exhibited medium high level (weak positive), while 3.5% of tumor tissues and 64% of normal tissues was negative in SIRT3 expression." (PMID 26121691, 2015). "This was not evident for patients whose tumours expressed high levels of SIRT3." (PMID 26121130, 2015). "However, this is not totally surprising considering the large number of SIRT3 substrates that, once deacetylated, can act as tumor promoters or suppressors, with the final outcome probably related to which pathway is exploited by the tumor cells." (PMID 38931477, 2024). "We previously showed that mice lacking Sirt3 develop ER+ luminal B-like tumor properties, suggesting that MnSOD, perhaps when acetylated, may function as a tumor promoter, instead of its more traditional function as a detoxification enzyme and tumor suppressor (TS)." (PMID 35453320, 2022). "Furthermore, the tumor suppressive effects of Sirt3 could be partially reversed by E2 treatment, but this is not sufficient to rescue the full tumorigenic potential of these cells." (PMID 32244715, 2020). "Analysis of patients who received chemotherapy revealed no survival difference between those whose tumours expressed low or high SIRT3 protein levels, suggesting that chemotherapeutics may contribute to alleviating the negative effects of reduced SIRT3 expression." (PMID 26121130, 2015). "Therefore, mice lacking the mitochondrial Sirt3 gene were established to determine whether SIRT3 is a TS protein, in which case, cells or mice lacking Sirt3 would likely display a tumor-permissive phenotype." (PMID 25332769, 2014). "The expression of SIRT1–7 was not correlated with the survival of the patients; however, SIRT3 and SIRT7 expression was significantly correlated with the proliferation marker Ki-67, implying roles in tumor cell proliferation." (PMID 33669567, 2021). "Mouse embryonic fibroblasts (MEF) overexpressing Myc/Ras developed into tumors when implanted in the hind limb of mice, whereas mice implanted with SIRT3+/+ Myc/Ras, SIRT3−/− Myc, or SIRT3−/− Ras MEFs did not, thus asserting tumor suppressor activity of SIRT3." (PMID 28423723, 2017). "To determine whether the CT inhibited the expression of STAT3, SIRT3, HIF‐1α, GLUT1, LDHA, and HK2 in vivo, we performed qRT‐PCR to detect these genes expression in tumor tissues from the mouse with or without the treatment of CT." (PMID 30094960, 2018).
tumor (continued). "Consequently, an increased SIRT3 level may characterize metastatic LUAD, whose cells spread to the lymph nodes without forming an extensive primary tumor site." (PMID 37749074, 2023). "Hence, the absence of TRAP1 could display its anti-tumor effect not only by inducing SDH and down-regulating the intracellular concentration of the oncometabolite succinate, but also by increasing NAD+/NADH ratio and the consequent SIRT3 activity via complex I induction." (PMID 35393510, 2022).
cancer (277 papers, 2006 to 2026). A tumor composed of atypical neoplastic, often pleomorphic cells that invade other tissues. "Analysis of TCGA data showed that high TFAM-SIRT3 co-expression is associated with overall survival across cancers, particularly in Kidney Renal Clear Cell Carcinoma (KIRC), where TFAM is downregulated (whereas SIRT3 is not)." (PMID 42014678, 2026). "In various types of cancers, the loss of SIRT3 triggers the reprogramming of glycolytic metabolism and increases the level of ATP and the content of lactate, thus promoting tumorigenesis." (PMID 40252727, 2025). "SIRT3, a member of the Sirtuin family, encodes a mitochondrial protein that can eliminate reactive oxygen species, inhibit cell apoptosis, and prevent cancer cell formation." (PMID 40511304, 2025). "Sirt3 depletion causes HIF1α stabilization via an increase in reactive oxygen species in cancer cells, whereas HIF1α depletion results in increased expression of Sirt3 in skeletal muscle." (PMID 40308032, 2025). "In particular, the well-known SIRT3 activator honokiol shows promise for treating illnesses linked to inflammation, cardiac problems, cancer, and metabolic issues." (PMID 40338931, 2025). "SIRT3 is associated with a variety of cancers, and in many cancers, the loss of SIRT3 triggers metabolic reprogramming that promotes tumorigenesis." (PMID 40252727, 2025). "The sensitivity of SIRT3-deficient cells to IR and other DNA-damaging agents represents a promising therapeutic strategy, particularly in the context of cancer treatment." (PMID 39002667, 2024). "When SIRT3 is deficient, the impairment of mitochondrial respiration and increased ROS production were reported in myoblasts and cancer cells." (PMID 39683482, 2024). "This dualistic effect of SIRT3 is closely associated with the metabolic requirements of cancer cells, which pivot between aerobic glycolysis and oxidative phosphorylation for energy production." (PMID 38773972, 2024). "Although SIRT3 has been linked to cancer in certain studies, its utility as a therapeutic target remains debatable." (PMID 38816444, 2024). "In previous studies, SIRT3 deficiency caused mitochondrial respiration impairment and elevated reactive oxygen species (ROS) production in myoblasts and cancer cells." (PMID 38294557, 2024). "The association between cancer and several other mitochondrial-related proteins, such as silent information regulator 3 (SIRT3), mitochondrial tumor suppressor gene 1 (MTUS1), and 8-hydroxyguanine DNA glycosylase (OGG1), has been reported." (PMID 37627097, 2023). "Recent advances have revealed that the loss of mitochondrial sirtuin function, especially that of SIRT3, is associated with many age-related diseases, including cancer, insulin resistance, heart disease, fibrosis and neurodegeneration." (PMID 37196115, 2023). "Further, the loss of Sirt3 accelerates the development age-related disorders, such as neurodegenerative diseases, cardiovascular diseases, and cancers." (PMID 36739437, 2023). "Several studies have shown the association of SIRT3 with different human diseases, including age-related diseases, cancer, heart and metabolic diseases." (PMID 35328633, 2022). "Compound 3-O-chloroacetyl-gagamine (A671) binds and activates SIN3 Associated Protein 18 (SAP18) to inhibit the SIRT3 transcription, which has a good anti-cancer effect in T-cell lymphoma and erythroleukemia." (PMID 35832551, 2022). "Previous studies confirmed that SIRT3 regulates a wide range of metabolic pathways involved in the cancer progression, and responds to nutrient deficiency (30, –, 33)." (PMID 35019690, 2022). "SIRT3 is induced by PGC1A, and the expression of PGC1A, similarly to the expression of SIRT3, has been both positively and negatively linked to cancer." (PMID 34831420, 2021).
cancer (continued). "Accumulating evidence has recently documented that SIRT3 is associated with many types of human diseases, including age-related diseases, cancer, heart disease and metabolic diseases, indicating that SIRT3 can be a potential therapeutic target." (PMID 32724473, 2020). "The ablation of SIRT3 causes pleiotropic effects in cancer but typically SIRT3 acts as a tumor suppressor protein." (PMID 31847543, 2020). "The role of SIRT3 in cancer is a double-edged sword which to some extent increases the confusion and risk of SIRT3 as a target for cancer treatment." (PMID 32724473, 2020). "This is consistent with previous studies showing that SIRT3 regulates fatty acid oxidation, while Perturbations in fatty acid metabolism have been associated with cancer." (PMID 31970087, 2019). "Five HDAC genes (HDAC2, HDAC4, HDAC5, HDAC10, and SIRT3) showed copy number loss in at least two cancer types." (PMID 30760718, 2019). "KO mouse embryonic fibroblasts showed increased glycolysis and decreased mitochondrial oxidative metabolism, and mice deficient in SIRT3 showed increased propensity to develop cancers." (PMID 28423723, 2017). "Loss of SIRT3 results in increased ROS production, resulting in HIF1α stabilization, followed by transcriptional induction of various cancer promoting genes and a shift in metabolism towards glycolysis (Warburg effect)." (PMID 28423723, 2017). "A total of 14 studies comprising 2165 cancer patients were included to assess the association between SIRT3 immunohistochemical expression and overall survival or clinicopathological characteristics." (PMID 27483432, 2016). "Total effect analyses and subgroup analyses (by cancer type) were used to assess the association between SIRT3 expression and clinicopathological parameters in various cancer patients." (PMID 27483432, 2016). "This meta-analysis indicates that SIRT3 expression level is associated with prognostic and clinical features in specific cancers." (PMID 27483432, 2016). "Overexpression of SIRT3 or MnSOD, or treatment with the antioxidant N-acetylcysteine, reduces ROS levels and cellular proliferation in SIRT3-deficient mouse embryonic fibroblasts and in cancer cells." (PMID 25085992, 2014). "Our results suggest that SIRT3 can inhibit the formation of ROS, which are implicated in aging and cancer." (PMID 20661474, 2010). "For example, this region harbours the SIRT3 gene, which has been associated with cancer and whose expression showed correlation with copy number loss together with RIC8A." (PMID 19432969, 2009). "Cancer-promoting and inhibitory effects have been implicated for SIRT3." (PMID 36497084, 2022). "Studies have shown increased, decreased, and mutated SIRT3 in a variety of cancers." (PMID 34831420, 2021). "We thought that such a discrepancy may be caused by different regulatory role of SIRT3 in different types of cancer." (PMID 28947845, 2017). "This might indicate the association of SIRT3 expression and overall survival in cancer patients was depended on the cancer type." (PMID 27483432, 2016). "In addition, lack of or lower expression of SIRT3 is detected in several human cancers and SIRT3 level is associated with the sensitivity of cancer cells to chemo- and radiotherapy." (PMID 26121691, 2015). "However, SIRT3 is also shown be overexpressed in human cancers and associated with therapy resistance." (PMID 26121691, 2015). "Future studies screening a larger number of OSCC patients for SIRT3 mutations to highlight important genetic alterations may help identify useful targets for personalized cancer therapy and more successful cancer treatment." (PMID 23800187, 2013).